TESMIN (testis expressed metallothionein like protein)
Description:
Essential for normal spermatogenesis and male fertility (By similarity). Required for the completion of meiosis in male germ cells (By similarity).
Synonyms: MTL5; CXCDC2; MTLT
Tractability: PROTAC: ubiquitination databases record sites on it.
Gene: Protein-coding gene on chromosome 11 (68,707,440 to 68,751,568, reverse strand). Ensembl gene ENSG00000132749.
Subcellular location: Cytoplasm; Nucleus
Subcellular location (Human Protein Atlas): Nucleoplasm; Cytosol; Vesicles
Gene Ontology:
Molecular function: protein binding; metal ion binding
Biological process: intracellular monoatomic cation homeostasis; male meiotic nuclear division; regulation of DNA-templated transcription; response to metal ion; spermatogenesis
Cellular component: cytoplasm; nucleus
Genetic constraint (gnomAD): Loss-of-function variants: 29 observed, 38.77 expected, observed/expected ratio (o/e) 0.75, 90% interval 0.56 to 1.02. The synonymous counts are far from expectation, so gnomAD's model fits this gene poorly and the ratio says little. Missense variants: 541 observed, 537.57 expected, observed/expected ratio (o/e) 1.01, 90% interval 0.94 to 1.08. Synonymous variants: 261 observed, 213.08 expected, observed/expected ratio (o/e) 1.22, 90% interval 1.11 to 1.36.
Homologues: Orthologues: chimpanzee TESMIN (98% identical), macaque TESMIN (94% identical), dog TESMIN (79% identical), pig TESMIN (79% identical), rabbit TESMIN (64% identical), mouse Tesmin (64% identical), rat Tesmin (63% identical), guinea pig TESMIN (60% identical), Drosophila melanogaster mip120 (26% identical), zebrafish tesmin (26% identical), Caenorhabditis elegans lin-54 (21% identical). Paralogues in human: LIN54 (35% identical).
Diseases named in the same sentence as TESMIN in open-access papers:
TESMIN is named in the same sentence as 12 diseases in open-access papers, as found by Europe PMC text mining. Sharing a sentence is not in itself a finding about the gene and the disease.
TESMIN shares sentences with these, for which no sentence is quoted: B-cell acute lymphoblastic leukemia (2 papers); breast carcinoma (2); tumor (2); acute lymphoblastic leukemia (1); Azoospermia (1); cancer (1); cervical squamous cell carcinoma (1); hepatocellular carcinoma (1); lung adenocarcinoma (1); lung carcinoma (1); male infertility (1); osteoporosis (1).